BABAM2 (BRISC and BRCA1 A complex member 2)
Description:
Component of the BRCA1-A complex, a complex that specifically recognizes 'Lys-63'-linked ubiquitinated histones H2A and H2AX at DNA lesions sites, leading to target the BRCA1-BARD1 heterodimer to sites of DNA damage at double-strand breaks (DSBs). The BRCA1-A complex also possesses deubiquitinase activity that specifically removes 'Lys-63'-linked ubiquitin on histones H2A and H2AX. In the BRCA1-A complex, it acts as an adapter that bridges the interaction between BABAM1/NBA1 and the rest of the complex, thereby being required for the complex integrity and modulating the E3 ubiquitin ligase activity of the BRCA1-BARD1 heterodimer. Component of the BRISC complex, a multiprotein complex that specifically cleaves 'Lys-63'-linked ubiquitin in various substrates. Within the BRISC complex, acts as an adapter that bridges the interaction between BABAM1/NBA1 and the rest of the complex, thereby being required for the complex integrity. The BRISC complex is required for normal mitotic spindle assembly and microtubule attachment to kinetochores via its role in deubiquitinating NUMA1. The BRISC complex plays a role in interferon signaling via its role in the deubiquitination of the interferon receptor IFNAR1; deubiquitination increases IFNAR1 activity by enhancing its stability and cell surface expression. Down-regulates the response to bacterial lipopolysaccharide (LPS) via its role in IFNAR1 deubiquitination. May play a role in homeostasis or cellular differentiation in cells of neural, epithelial and germline origins. May also act as a death receptor-associated anti-apoptotic protein, which inhibits the mitochondrial apoptotic pathway. May regulate TNF signaling through its interactions with TNFRSF1A; however these effects may be indirect.
Synonyms: BRCC45; BRE; BRCC4
Tractability: Small molecule: a structure with a bound ligand is known. PROTAC: ubiquitination databases record sites on it.
Gene: Protein-coding gene on chromosome 2 (27,888,667 to 28,338,901, forward strand). Ensembl gene ENSG00000158019.
Subcellular location: Cytoplasm; Nucleus
Subcellular location (Human Protein Atlas): Cytosol
Pathways (Reactome):
DNA Repair: Nonhomologous End-Joining (NHEJ); Processing of DNA double-strand break ends; Recruitment and ATM-mediated phosphorylation of repair and signaling proteins at DNA double strand breaks
Cell Cycle: G2/M DNA damage checkpoint
Metabolism of proteins: Metalloprotease DUBs
Gene Ontology:
Molecular function: polyubiquitin modification-dependent protein binding; protein binding; tumor necrosis factor receptor binding; peroxisome targeting sequence binding
Biological process: cellular response to ionizing radiation; DNA damage response; double-strand break repair; mitotic G2 DNA damage checkpoint signaling; negative regulation of apoptotic process; positive regulation of DNA repair; response to ionizing radiation; mitotic G2/M transition checkpoint; protein K63-linked deubiquitination; regulation of DNA damage checkpoint; regulation of DNA repair; response to vitamin B6; signal transduction
Cellular component: BRCA1-A complex; BRISC complex; cytoplasm; cytosol; nuclear ubiquitin ligase complex; nucleus; nucleoplasm
Genetic constraint (gnomAD): Loss-of-function variants: 28 observed, 50.98 expected, observed/expected ratio (o/e) 0.55, 90% interval 0.41 to 0.75. The upper end of that interval is the gene's LOEUF score, 0.75, which puts it in group 3 of 6, group 1 being the genes least tolerant of losing a copy. Missense variants: 361 observed, 469.89 expected, observed/expected ratio (o/e) 0.77, 90% interval 0.7 to 0.84. Synonymous variants: 166 observed, 169.47 expected, observed/expected ratio (o/e) 0.98, 90% interval 0.86 to 1.11.
Homologues: Orthologues: pig BABAM2 (99% identical), macaque BABAM2 (99% identical), mouse Babam2 (99% identical), rabbit BABAM2 (99% identical), chimpanzee BABAM2 (97% identical), tropical clawed frog babam2 (93% identical), rat Babam2 (92% identical), guinea pig BABAM2 (92% identical), zebrafish babam2 (84% identical).
Diseases named in the same sentence as BABAM2 in open-access papers:
BABAM2 is named in the same sentence as 11 diseases in open-access papers, as found by Europe PMC text mining. Sharing a sentence is not in itself a finding about the gene and the disease. The quoted sentences say what the papers report.
lung carcinoma (1 paper, 2022). "In summary, this study revealed that the expression of PPDPF is upregulated in lung cancer and inhibits the degradation of BABAM2, thereby enhancing the resistance of lung cancer cells to radiotherapy." (PMID 34975328, 2022). "Mechanistically, PPDPF interacted with BABAM2 (an antiapoptotic protein) and blocked its ubiquitination by MDM2, thus stabilizing BABAM2 and promoting the radioresistance of lung cancer cells." (PMID 34975328, 2022). "In the molecular mechanistic study, PPDPF was found to inhibit apoptosis via stabilizing BABAM2 and to enhance the radioresistance of lung cancer cells." (PMID 34975328, 2022). "A crucial finding in this study was that PPDPF inhibits the apoptotic pathway via stabilizing BABAM2, making lung cancer cells resistant to radiotherapy." (PMID 34975328, 2022). "BABAM2 formed a complex with endogenously expressed MDM2 in lung cancer cells." (PMID 34975328, 2022). "Furthermore, endogenously expressed PPDPF and BABAM2 formed a complex in lung cancer cells." (PMID 34975328, 2022). "In the xenografts formed from cells with PPDPF knockdown, the IHC results showed that the expression of BABAM2 and Bcl-xl was downregulated and that cleaved Caspase3 was upregulated, further demonstrating that downregulation of PPDPF inhibited the tumorigenesis of lung cancer cells in vivo." (PMID 34975328, 2022).
septic arthritis (1 paper, 2022). "In this study, we constructed a LPS-induced osteolytic model that mimics septic arthritis 8, 12 to validate if Babam2 overexpression could prevent pathological bone resorption." (PMID 35864959, 2022).
tumor (4 papers, 2013 to 2020). "BABAM2 at 2p23.2 encodes a death receptor-associating intracellular protein that promotes tumor growth by suppressing apoptosis." (PMID 31649266, 2019).
cancer (2 papers, 2020). A tumor composed of atypical neoplastic, often pleomorphic cells that invade other tissues. "Moreover, several cancer cell types strongly expressed BABAM2 and overexpression of BABAM2 promoted the growth of tumors." (PMID 33050379, 2020). "It has been reported that UV radiation treatment of cancer cells inhibited Babam2 mRNA expression." (PMID 33050379, 2020).
BABAM2 also shares sentences with these, for which no sentence is quoted: breast carcinoma (4 papers); benign tumors (1); esophageal carcinoma (1); esophageal squamous cell carcinoma (1); glioma (1); osteoporosis (1); ovarian carcinoma (1).